BMI1 (BMI1 proto-oncogene, polycomb ring finger)
Diseases named in the same sentence as BMI1 in open-access papers (continued):
Sharing a sentence is not in itself a finding about the gene and the disease.
breast carcinoma (continued). "Overexpression of Bmi-1 induces telomerase activity and immortalizes human mammary epithelial cells (MECs), suggesting a potential role for Bmi-1 in the development of human breast cancer." (PMID 21637439, 2009). "The results obtained suggest that targeting of Bmi-1 may be used as a potential and specific therapeutic tool for the treatment of breast cancer." (PMID 21637439, 2009). "Previous reports indicated that the BMI1 gene may be a novel molecular marker to predict the progression and prognosis of breast cancer and myelodysplastic syndrome (MDS)." (PMID 19228380, 2009). "Interestingly, although EZH2 overexpression correlates with a poor prognosis in breast cancer, BMI1 overexpression correlates with a good outcome." (PMID 19099573, 2008). "This is the first study that evaluates Bmi-1 in plasma by using a large series of primary breast carcinomas to investigate the presence at diagnosis of detectable Bmi-1 mRNA in plasma and possible correlations between this event and a series of clinical-pathological parameters of the tumors." (PMID 17711569, 2007). "Thus, we attempted to detect Bmi-1 mRNA in plasma from a large series of 111 patients with primary breast carcinomas to assess its possible value as a prognostic marker and its applicability as a noninvasive tool for prognosis." (PMID 17711569, 2007). "Moreover, we described for the first time a statistically significant correlation between Bmi-1 expression in plasma of breast cancer patients and disease-free and overall survival in advanced stages." (PMID 17711569, 2007). "However, the effect of Bmi-1 overexpression on the inactivation of the INK4a/ARF transcripts in human breast cancer is unclear." (PMID 17711569, 2007). "Moreover, we described for the first time a statistically significant correlation between Bmi-1 expression in plasma of breast cancer patients and survival in advanced stages." (PMID 17711569, 2007). "We evaluated for the first time the oncogene Bmi-1 in plasma in a large series of primary breast carcinomas to investigate the presence at diagnosis of detectable Bmi-1 mRNA in plasma and its possible correlations with clinical-pathological parameters of the tumors and survival of patients." (PMID 17711569, 2007). "Furthermore, FUNDC1-involved MAMs can promote calcium transport to cytoplasm, making nuclear factor of activated T cells 1 (NFATC1) dephosphorylated, and then Bmi1 polycomb ring finger oncogene (BMI1) is upregulated, thus promoting the progression of breast cancer." (PMID 35959490, 2022). "Thus, we suggest that high BMI1 expression with a low CD8+ T cell count could promote breast cancer cell survival." (PMID 34442383, 2021). "We suggest that high BMI1 expression could be a therapeutic target in breast cancer." (PMID 34442383, 2021). "BMI1 could play a critical role in the development of breast cancer." (PMID 34442383, 2021). "Furthermore, IL1β treatment could induce icd‐IL1R2 release in a time‐ and dose‐dependent manner in IL1R2‐overexpressing breast cancer cells, and IL1R2 neutralizing antibody pretreatment reversed IL1β induced BMI1 upregulation in breast cancer cells." (PMID 31921558, 2020). "The PANDAR/Bmi1/p16INK4A axis could serve as novel targets for breast cancer therapy." (PMID 26927017, 2016). "Aberrant expression of Bmi-1 has been detected in several human cancers including lymphoma, acute myeloid leukemia, colorectal carcinoma, liver carcinoma, non-small cell lung cancer, breast carcinoma, prostate cancer, head and neck squamous cell carcinoma, medulloblastoma, and glioblastoma." (PMID 26894855, 2016). "Since then, Bmi1 has been associated with several cancers including non-small cell lung cancer, ovarian cancer, acute myeloid leukemia, nasopharyngeal carcinoma, neuroblastoma, glioblastoma, and breast cancer." (PMID 25348805, 2014). "Therefore, the exact role of ERα coupled Bmi1 pathway in breast cancer need to be further explored." (PMID 24559156, 2014).
breast carcinoma (continued). "Results strongly suggest the ERα-coupled Bmi1 regulatory pathway may be one of the main regulatory mechanisms in breast cancer, whose activity determines the down-stream gene status of p16INK4a and cyclin D1, and consequently impacts the biologic behavior of breast cancer." (PMID 24559156, 2014). "This suggested Bmi1 could be used as a prognostic marker in breast cancer patients." (PMID 25348805, 2014). "To investigate Bmi1 expression in Indian breast cancer patient samples, we undertook quantitative real time PCR (qPCR) and immunohistochemistry (IHC) based analyses in primary breast cancer samples that were predominantly grade III invasive ductal breast adenocarcinomas." (PMID 25348805, 2014). "If Bmi1 is a key player responsible for the crosstalk between these self-renewal pathways, targeting Bmi1 could be an ideal way of targeting these pathways that are activated in breast cancer stem cells." (PMID 25348805, 2014). "However, the relationship between BMI1 expression and prognosis in breast cancer remains controversial: although it has been reported that BMI1 is overexpressed in advanced stages of breast cancer, BMI1 expression has been linked to good outcome in breast cancer." (PMID 24742605, 2014). "miR-128 is known to target Bmi1, the polycomb transcription factor required for stemness, and miR-128 expression may be increased during the transition from the cancer-initiating cell state to the expansive state of breast cancer." (PMID 24485087, 2014). "Therefore, it is important to understand whether Bmi-1 can regulate EMT during breast cancer progression and metastasis." (PMID 21276221, 2011). "However, the underlying molecular mechanism of Bmi-1-mediated progression and the metastasis of breast cancer are not fully elucidated at this time." (PMID 21276221, 2011). "However, to further confirm Bmi-1 expression in breast cancers, multi-center studies are required." (PMID 21276221, 2011). "Interestingly, we have found that Bmi-1 is negatively regulated by Mel-18 and expression of Mel-18 negatively correlates with Bmi-1 in breast tumors, and Mel-18 overexpression in breast cancer cell line MCF7 results in downregulation of Bmi-1 and reduction of transformed phenotype." (PMID 21059209, 2010). "Finally, we identified a possible mechanism to explain why BMI1 overexpression may contribute to a better outcome than EZH2 overexpression in breast cancer." (PMID 19099573, 2008). "The lack of association between BMI-1 and p16 expression has also been reported for breast cancer, lung cancer, and Hodgkin's lymphoma, whereas in oral cancer and nasopharyngeal cancer, BMI-1 has been indicated to act through p16 to regulate cellular proliferation." (PMID 18475299, 2008). "Elevated expression of human BMI-1 has also been reported in multiple cancer samples by immunohistochemistry or mRNA analysis for oral cancers, lung cancers, lymphomas, and breast cancer as well as in cancer cell lines, although the exact function is not known." (PMID 18475299, 2008). "Thus, the plasma of breast cancer patients had the absence or presence of Bmi-1 expression." (PMID 17711569, 2007). "Inhibition of miR-494-3p partially reversed the inhibitory effects of hinokitiol on B lymphoma Mo-MLV insertion region 1 homolog (BMI1) expression and mammosphere formation in breast cancer cells." (PMID 41226811, 2025). "Evidence demonstrates that in breast cancer, the overexpression of β-TRCP can result in reduced production of BMI1." (PMID 39744574, 2025). "Promotion of Akt activity by Bmi1 was also found to promote EMT by blocking the GSK3β-mediated degradation of Snail in HNSCC and breast cancer." (PMID 38002001, 2023). "The inhibition of BMI1 also suppresses CSC characteristics and tumor growth in colorectal cancer, breast cancer, HCC, glioblastoma and neuroblastoma." (PMID 35455671, 2022).
breast carcinoma (continued). "We performed qRT-PCR for the major stemness-related transcription factors, such as NANOG, SOX2, OCT4 and BMI1, as well as the marker CD44, a panel that predicts a transcriptional shift to a stem-like state in breast cancer cells." (PMID 35195687, 2022). "For the route blocking transcription, broad spectrum histone deacetylase (HDAC) inhibitors have been shown to inhibit the expression of BMI1 and the activity of the PRC1 complex in breast cancer cells, as measured through a decrease of H1AK119ub1." (PMID 33804165, 2021). "A transcriptomic meta-analysis of breast cancer patients showed that PD-L1 regulated the expression of OCT4A, Nanog, and BMI1 through AKT signaling." (PMID 35071018, 2021). "PcG of proteins, such as BMI1 (B lymphoma Mo-MLV insertion region homolog), a component of the PRC1, and EZH2 (PRC2), are upregulated in breast cancer and BCSCs." (PMID 34360879, 2021). "This review focuses on roles of miRNAs in breast cancer progression, particularly their involvement in Wnt/β-catenin, Notch, PI3K/AKT/mTOR, BMI-1 and STAT3 pathways in breast cancer stem cells (BCSCs)." (PMID 33413418, 2021). "In breast cancer, Wnt5a binding to ROR1 increases BMI-1 levels and this process was dependent on AKT phosphorylation." (PMID 31382410, 2019). "It has been reported that PTC-209 at a similar concentration used in our study was able to decrease Bmi-1 protein expression in both MDA-MB-231 and MCF-7 breast cancer cells and A549 lung cancer cells." (PMID 31695609, 2019). "So, we proposed that BMI‐1 gene might not be a breast cancer‐susceptibility candidate." (PMID 29691986, 2018). "Bmi1 was downregulated using two approaches in the mouse breast cancer stem cell line FMMC 419II—a small molecule inhibitor (PTC 209) and stable transfection with a Bmi1 shRNA plasmid." (PMID 28418883, 2017). "This study presents the tumor-suppressive function of miR-494-3p in breast cancer by inhibiting BCSC self-renewal and directly targeting BMI1." (PMID 29100291, 2017). "B cell-specific Moloney murine leukemia virus integration site (Bmi)-1 is a critical inducer of cell adhesion, migration, and invasion as well as the epithelial-mesenchymal transition (EMT) in human breast cancer cells." (PMID 27384474, 2016). "In particular, Bmi1 has been identified as a key therapeutic target in CRC, and has been shown to be overexpressed in drug resistant breast cancer." (PMID 26930714, 2016). "The current findings highlight the critical role of Bmi1 in regulating both EMT and stemness in breast cancer cells." (PMID 26023734, 2015). "In this report, we investigated the effect of IR on the expression of Bmi-1 and its effect on EMT and metastasis of breast cancer cells in a time-dependent manner." (PMID 25734775, 2015). "Knockdown of Bmi-1 using Bmi-1-targeting shRNA totally abolished the effect of the IR on the EMT process and migration of breast cancer cells." (PMID 25734775, 2015).
breast carcinoma (continued). "Next, we investigated the role of Bmi1 in ERα-mediated suppression of EMT and stemness properties in breast cancer cells." (PMID 26023734, 2015). "In the current study, we have demonstrated that ERα can suppress Bmi1 expression by transcriptional repression, and inhibit EMT and stemness in breast cancer through an ERα-Bmi1-E-cadherin pathway." (PMID 26023734, 2015). "In accordance with this notion, ectopic BMI1 decreased γH2AX in MCF7 breast cancer and DU145 prostate cancer cells in response to etoposide-induced DSBs, while BMI1 knockdown in both lines enhanced the γH2AX production and its nuclear foci." (PMID 26633535, 2015). "Our results thus far implied that Bmi1 plays a crucial role in self-renewal, EMT and drug-resistance of breast cancer cells - the properties attributed to tumor-initiating cells." (PMID 25348805, 2014). "The expression of Bmi1 and its correlation with ERα, PR, Ki-67, HER2, p16INK4a, cyclin D1 and pRB was evaluated by immunohistochemistry in a collection of 92 cases of breast cancer and statistically analyzed." (PMID 24559156, 2014). "Further, we assessed the effects of Bmi1 overexpression and shRNA-mediated knockdown on stemness, self-renewal, EMT and drug-resistance of breast cancer cells." (PMID 25348805, 2014). "Many individual markers such as stem cell marker Bmi-1, lysyl oxidase-like 2 (LOXL2), FOXC1, α9β1 integrin, and monocarboxylate transporter 1 were studied to find specific markers for basal-like breast carcinoma." (PMID 25510449, 2014). "Up to now, the role of Polycomb in breast cancer has been mainly addressed to investigate the expression or the function of two Polycomb proteins, EZH2 and BMI1 (PRC2 and PRC1 complexes, respectively)." (PMID 24742605, 2014). "GE treatment led to increased expression of tumor suppressor genes, p16 and p21, whereas it decreased expression of tumor promoting genes, BMI1 and c-MYC, in both precancerous SH and breast cancer SHR cells at the mRNA." (PMID 23342141, 2013). "Bmi-1 expression was low in p16-negative immortalized 76N-TERT and MCF-10A cells and moderate in 76R-30 cells, whereas it was abundant in all breast cancer cell lines analyzed, including SK-BR-3, ZR-75-30, BCAP-37 and MDA-MB-435S." (PMID 21276221, 2011). "Conversely, RNA interference was used to decrease the expression of Bmi-1 in MDA-MB-435S, an estrogen-independent breast cancer cell line derived from a mammary ductal carcinoma." (PMID 21276221, 2011). "Bmi-1 is negatively correlated with the expression of E-cadherin, which is important for EMT in breast cancer." (PMID 21276221, 2011). "We have reported that Mel-18 functions as a potential tumor suppressor by repressing the expression of BMI1 and consequent downregulation of activated AKT in breast cancer cells." (PMID 20170541, 2010). "In order to investigate the possibility of turning Bmi-1 into a novel therapeutic agent for the treatment of breast cancer, MCF-7 was chosen to silence the expression of Bmi-1 with the highly specific post-transcriptional suppression of RNAi." (PMID 21637439, 2009). "The effect in MDA-MB-231 breast cancer cells was somewhat weaker, LD50VM26 of 3.9 μM with Bmi1 siRNA compared to 7.2 μM with control siRNA." (PMID 19956605, 2009). "Polycomb-group genes such as BMI1, EZH2 and SUZ12 have repeatedly been identified as adverse prognostic factors in breast cancer." (PMID 17573968, 2007). "Additionally, other markers for CSCs in breast cancer have been reported, including Ep-CAMhi, the CD44hi/CD24lo-Ep-CAMhi combination, CD10, CD24hi, and BMI1." (PMID 40943144, 2025).
breast carcinoma (continued). "Twist and Bmi1 also mediate suppression of a micro-RNA, miR let-7i, which results in NEDD9 and DOCK3 overexpression and promotes mesenchymal motility in HNSCC, melanoma, and breast cancer via Rac1." (PMID 38002001, 2023). "In breast cancer and oral squamous cell carcinoma, changes in Bmi-1 expression did not affect p16Ink4a expression, suggesting that the oncogenic activity of Bmi-1 functions through a p16Ink4a-independent signaling pathway." (PMID 36726797, 2023). "Moreover, a high expression of BMI1 is correlated with decreased CD4+/CD8+ T cells in the TME and predicts a poor disease-free survival in patients with breast cancer." (PMID 35455671, 2022). "While BMI1 has been reported to be regulated in protein stability by β‐TrCP E3‐ligase in breast cancer, our study of co‐immunoprecipitation (co‐IP) Western blot showed that BMI1 and β‐TrCP did not physically interact." (PMID 35794816, 2022). "Moreover, the expressional levels of FOXC1 gene is negatively related with that of Polycomb group (PcG) genes, i.e., Bmi1, EZH2, and SUZ12, in breast cancer cells." (PMID 34167089, 2021). "BMI-1 is an oncoprotein involved in cell cycle regulation and cell immortalization, and its up-regulation has been reported in acute myeloid leukemia (AML) and lung, ovarian, nasopharyngeal, and breast carcinomas." (PMID 32742599, 2020). "Recently, the expression of FUN14 domain-containing protein 1 was positively correlated with breast cancer metastasis and the Ca2+/NFATC1/BMI1 axis, suggesting that inhibition of this protein could represent a therapeutic target for breast cancer." (PMID 33511135, 2020). "Interestingly, in tumors such as breast cancer, enhanced ROR1 expression promotes tumorigenesis through the upregulation of YAP/TAZ transcription and/or polycomb complex protein BMI-1 expression." (PMID 31382410, 2019). "To investigate whether BMI1 is involved in ssDNA-stimulated DDR, we have constructed MCF7 breast cancer and DU145 prostate cancer cell lines in which BMI1 was either stably overexpressed or knocked-down." (PMID 29163782, 2017). "To investigate the effect of ERα on Bmi1 expression in an ERα-negative breast cancer cell line, we stably transfected the recombinant vector pEGFP-C1-ERα, or an empty vector, into ERα-negative BT549 cells." (PMID 26023734, 2015). "We found that Bmi1 expression was higher in three ERα-negative breast cancer cell lines (SKBR3, BT549, and MDA-MB-231) than in ERα-positive T47D or BT474 cells." (PMID 26023734, 2015). "To determine the potential role of Bmi-1 in regulation of IR-induced vimentin expression and EMT of breast cancer cells, we analyzed the correlation of the expression levels of Bmi-1 with vimentin and E-cadherin in MDA-MB-231 and Hs578t cells after IR (2 Gy) in a time-dependent manner." (PMID 25734775, 2015). "BMI1 is upregulated in a variety of cancer types, including lymphomas, prostate cancer, non-small cell lung cancer (NSCLC), colon cancer, breast cancer, and nasopharyngeal carcinoma." (PMID 26633535, 2015). "Consistent with Bmi1 protein expression, Bmi1 mRNA levels were 2 to 3 fold higher in ERα-negative breast cancer cell lines than in in ERα-positive cells." (PMID 26023734, 2015). "Our findings indicate that ERα suppresses Bmi1 expression by directly binding to the half-ERE site of the BMI1 promoter, thereby demonstrating a novel pathway by which ERα suppresses migration, invasion, and EMT in breast cancer cells, in addition to modulating Slug and NF-κB pathways." (PMID 26023734, 2015).